TNF (tumor necrosis factor)
Diseases named in the same sentence as TNF in open-access papers (continued):
Sharing a sentence is not in itself a finding about the gene and the disease.
Arthritis (continued). "Moreover, as our colleagues proved Infliximab neutralizes human but not murine TNF, which makes it difficult to use it as a TNF biotherapy in CFA-induced arthritis to animals." (PMID 34163464, 2021). "Similarly, binding MTX to other macromolecules, such as anti-TNFα antibodies, might be clinically beneficial in autoimmune and inflammatory diseases such as arthritis, for example, where MTX is administrated at low dosages separately from anti-TNFα antibodies." (PMID 35056966, 2021). "Moreover, strychnine, brucine, and triptolide significantly inhibited the proliferation of fibroblast-like synoviocytes, and reduced the production of TNF-α and IL-6 and the mRNAs of TNF-α, IL-6, COX-2, and iNOS, suggesting that they possessed an anti-arthritis activity." (PMID 34108880, 2021). "Infliximab, an anti-TNF agent, has been shown to reverse muscle volume and strength in patients with Crohn’s disease; however, an anti-TNF intervention did not block muscle atrophy in an arthritis animal model." (PMID 34441751, 2021). "In addition, lower serum levels of TNF-α and IL-6 were also detected in the SPRC group, suggesting that SPRC treatment effectively ameliorated the symptoms and inflammatory responses of arthritis in AIA rats." (PMID 34422677, 2021). "In CIA mice, alantolactone at 50 mg/kg attenuated RA symptoms, including high arthritis scores, infiltrating inflammatory cells, synovial hyperplasia, bone erosion and levels of the proinflammatory cytokines TNF-α, IL-6 and IL-17A, but not IL-10 in paw tissues." (PMID 33556301, 2021). "However, since α2M has many functions it is unclear to what extent the arthritis-protective effects can be related to the direct inhibition of ADAMTS proteases or the interaction of α2M with inflammatory cytokines, such as IL-1β or tumor necrosis factor TNFα." (PMID 34268335, 2021). "Notably, IL-17 is capable of maintaining articular inflammation independent of TNFα once the arthritis is initiated." (PMID 34360720, 2021). "Furthermore, Haidalimumab could effectively neutralize recombinant human tumor necrosis factor alpha (rhTNFα) toxicity in a C57BL/6 mouse model and showed significant therapeutic effect in a tumor necrosis factor transgenic (TNF-Tg) mouse arthritis model." (PMID 34886761, 2021). "Notably, pathogenicity of disease in these spontaneous arthritis models is complex as, in some cases, disease is rescued by NLRP3 inflammasome deficiency rather than TNF loss, and vice versa." (PMID 33924766, 2021). "In the classic rat arthritis model for human RA, hAMSCs significantly ameliorated the severity of arthritis and decreased the histopathological changes due to dramatic inhibition of the production of proinflammatory cytokines, such as interferon-γ (IFN-γ) and tumor necrosis factor-α (TNF-α)." (PMID 33133012, 2020). "The importance of TNF-α was confirmed by experiments in which anti-TNF neutralizing antibodies were administered, which resulted in reductions in paw swelling, the histological severity of arthritis, and the clinical score for arthritis in a mouse model of CIA." (PMID 33198301, 2020). "However, without conditional peripheral inflammation, TNF has not been shown to elicit persistent pain in arthritis." (PMID 32038637, 2019). "They reported that trabeculectomy success rates at 1, 5, and 10 years after surgery were higher among patients treated with TNF inhibitors (at the time of their trabeculectomy to control uveitis, arthritis, or both) when compared with those who were not treated with TNF inhibitors." (PMID 31650812, 2019). "This implies that IL-6 and TNF-α may not be as important in lung inflammation as it is in arthritis." (PMID 30013577, 2018). "Moreover, the histological features of TNF-induced arthritis have not been changed by blocking IL-36 signaling pathways." (PMID 29416822, 2018).
Arthritis (continued). "The present study aimed to evaluate the anti-arthritis effects of the cardenolide-rich and caffeoylquinic acid-rich fractions (CDLFs and CQAFs) of P. forrestii in collagen-induced arthritic (CIA) rats, and defined the mechanisms of therapeutic action in MH7A cells treated with TNF-α." (PMID 30096961, 2018). "Indeed, in a model of arthritis, CCR1 blockade or depletion enhanced systemic TNF production." (PMID 29696014, 2018). "Interestingly, previous studies reported the presence of AT2R in the synovium of rats with adjuvant-induced arthritis as well as in cultured bovine chondrocytes stimulated with TNF-α or IL-1β pro-inflammatory cytokines, but not in unstimulated cells." (PMID 29038523, 2017). "The effect of low-dose (0.1 ppm) Cd was tested in an inflammatory context as would be the case in inflammatory joints, by adding or not the inflammatory cytokines IL-17 and TNF-α to synoviocytes from patients with RA and OA, a less inflammatory form of arthritis." (PMID 28546541, 2017). "TNF-α induces inflammation by activating NF-kB and AP-1, two key inflammatory mediators that activate the transcription of an array of inflammatory genes including cyclooxygenase-2 (COX-2), a target of a class of anti-arthritis medications, COXIBs such as celecoxib, etoricoxib and rofecoxib." (PMID 28771604, 2017). "Mice that overexpress TNF-α only in the lungs do not develop arthritis." (PMID 27450561, 2016). "In this study, we employ mice that overexpress TNF-α to determine if TNF-α can induce lung citrullination, if PAD4 is required for lung citrullination and/or lung inflammation downstream of TNF-α, and if TNF-α-induced lung inflammation is sufficient to induce arthritis." (PMID 27450561, 2016). "The infiltrated immune cells and synovial fibroblasts secrete various cytokines, like TNF-α, IL-1β, and IL-6, metalloproteinases (MMPs), and chemokines, such as MCP-1, MIP-1, and RANTES, in the inflamed joint tissues and eventually lead to arthritis including inflammation and bone erosion." (PMID 27840652, 2016). "Furthermore, blockade of IL-36 signaling did not change histological signs of TNF-induced arthritis." (PMID 25111378, 2014). "In murine collagen-induced arthritis (CIA), complete Freund's adjuvant (CFA)-induced paw inflammation in rat, rat AIA, and mouse K/BxN arthritis, the neutralization of TNF rapidly reduced inflammatory hyperalgesia in the absence of any other antinociceptive drugs." (PMID 25606597, 2014). "We next studied whether the intestinal epithelial-derived elevation in mucosal and systemic TNFα resulted in a specific disease phenotype in TNFi∆ARE/i∆ARE mice, using systemic TNFΔARE/+ mice as the reference model since these mice display an arthritis/ileitis inflammatory phenotype." (PMID 23977323, 2013). "Serum TNF-α level was below the lower limit of quantification (20 pg/mL) in all animals at all time points, and no changes that were considered to be related to onset of arthritis were noted in the other cytokines (data not shown)." (PMID 23834772, 2013). "Although IL-1 and TNFα, but not IL-6, were shown to be important in this arthritis model 13, it has not been clear whether IL-17 works in the effector phase of arthritis, regardless of the findings that non-T cells produce IL-17." (PMID 23671588, 2013). "Additionally, local therapy using anti-TNF biologics has not been evaluated in arthritis refractory to systemic anti-TNF therapy because many patients in successful cases were naïve to systemic anti-TNF biologics." (PMID 22551402, 2012). "However, it should be noted that in collagen-induced arthritis ATF-3 expression was not affected by anti-TNF therapy." (PMID 22769424, 2012). "However, injection of zymosan was not capable of sufficiently inducing TNFα and subsequent arthritis." (PMID 22613074, 2012). "Regardless, it is interesting to speculate that disruption of arthritis development by targeting TNFα-induced angiogenesis could be a valid, if not potent, therapeutic strategy." (PMID 22534470, 2012).
Arthritis (continued). "TNF-α was not only positively correlated with the number of TRAP+ osteoclast precursors (OCs) (r = 0.66; P = 0.000), but also with the radiographic damage scores (Sharp score r = 0.52; P = 0.001; BASRI r = 0.35; P = 0.02) and arthritis activity index PsAJAI (r = 0.41; P = 0.02)." (PMID 23144698, 2012). "Additionally, B cell depletion therapy with anti-CD20 antibodies sustained high LNCE of PLN, and anti-CD20 antibody treated TNF-Tg mice did not display asymmetric arthritis similar to the arthritic flare observed in the placebo group." (PMID 21884592, 2011). "TNF-α is a pro-inflammatory cytokine which may induce the proliferation of synoviocytes and enhance their production of cytokines such as TNF and IL-1 in situ, which largely show the pathology of arthritis." (PMID 21569552, 2011). "The central role for tumor necrosis factor-alpha (TNFα) in RA pathogenesis has been extensively demonstrated in experimental arthritis by successful treatment of murine collagen-induced arthritis (CIA) with TNFα antibodies and development of arthritis in transgenic mice overexpressing human TNF." (PMID 20370892, 2010). "Thus, inhibition of TNF production from immune complex-stimulated macrophages by GW2580 likely represents a primary mechanism by which Fms inhibition provides benefit in CAIA and K/BxN arthritis." (PMID 20181277, 2010). "Furthermore, CTLA-4-Ig was effective at inhibiting the TNF-induced osteoclast formation in a non-T cell-dependent TNF-induced model of arthritis, as well as at inhibiting the formation of inflammatory bone erosions in vivo." (PMID 19930661, 2009). "Monoclonal antibodies to TNF-α, IFN-γ, IL-12, CD40L, inducible co-stimulator (ICOS), and cytotoxic T-lymphocyte antigen 4 immunoglobulin (CTLA-4Ig) were used to block TNF-α and IFN-γ production, examine clinical index in mice with GPI-induced arthritis, and determine anti-GPI antibody production." (PMID 18534002, 2008). "We could not observe any significant differences regarding arthritis severity in mice receiving rHMGB1 between mice with or mice without the functional TNFα gene." (PMID 18582368, 2008). "The authors suggested that suppressing TNF-α and IL-1 may not be effective in the clinical treatment of Gram-positive bacteria-induced arthritis." (PMID 17129374, 2006). "This cytokine may not be necessary for the development of arthritis in this model, because a study recently reported that severe CIA occurs in TNF-α deficient mice." (PMID 16207337, 2005). "Anti-IL-1 and TNF-α therapies in animal arthritis models and anti-TNF-α in humans with RA have been shown to significantly reduce arthritis incidence, inflammation and joint destruction, suggesting that the mediating pathways of joint damage are, at least in part, mediated by IL-1 and/or TNF-α." (PMID 15642143, 2005). "The upregulated expression of TNF-α, IL-1α, IL-1β, IL-4R, P-selectin, MIP-1α (CCL3), MCP-1 (CCL2), NOS2 and NOS3 demonstrated in the present study is in agreement with previous observations of the dependency of the rat SCW-induced arthritis model on these mediators." (PMID 15642130, 2005). "Lastly, we addressed whether the absence of JNK1 influences cartilage damage in TNF-α-induced arthritis." (PMID 15642137, 2005). "Indirect evidence suggests that saffron can reduce pain scores and the number of swollen joints in patients with arthritis, but it does not significantly modulate serum markers, such as TNF-α and hs-CRP, implying that its anti-inflammatory mechanism may differ from that of conventional drugs." (PMID 40842498, 2025). "By establishing adjuvant induced arthritis model in rats and ovalbumin induced arthritis model in rabbits, we showed BBR-PPSG could effectively relieve joint swelling, inflammatory cell infiltration, reduce the levels of TNF-α and IL-1β, and maintain the stability of synovial chondrocytes." (PMID 37547331, 2023).
Arthritis (continued). "However, the occurrence of skin rash, arthritis, sore throat, lymphadenopathy, hepatosplenomegaly, leukocytosis, disease activity scores, and levels of ferritin, IL-1, IL-6, IL-17A, IL-18, TNF-α, LC3-II mRNA, or ATG16L mRNA expression was not predictive of the systemic pattern." (PMID 34208077, 2021). "In this study, we observed a negative correlation between TNF-α levels and the expression of special AT-rich sequence-binding protein 2 (SATB2), a critical osteoblastogenesis transcription factor, in ovariectomy (OVX)-induced bone loss and IL-1-induced arthritis animal model." (PMID 29435145, 2018). "Notably, the TNF-α protein levels were nearly undetectable in the synovial fluid from hind paws and in the plasma throughout the course of the arthritis, while the TNF-α gene transcription levels could only be measured in the early stages of arthritis." (PMID 28759646, 2017). "Also, TNF-α-induced lung inflammation is not sufficient to drive murine arthritis." (PMID 27450561, 2016). "The pristane-primed arthritogenic T cells which are used to transfer arthritis could secrete IFN-γ and TNF-α with Con A stimulation in vitro, and pretreatment of recipient rats with either anti-IFN-γ or a recombinant TNF-α receptor before transfer, ameliorated arthritis development." (PMID 21708001, 2011). "This pathway seems not to contribute to the pathology of arthritis during the stages of flare-up and acute inflammation, but may well propagate chronic catabolic processes in a joint, even when IL-1β or TNF-α are not expressed at pathological levels or are captured pharmacologically." (PMID 23675204, 2010). "Anti-TNF therapy for RA in the setting of HCV appears to be safe and well tolerated, without apparent influence on the underlying HCV infection; however, the usually nonaggressive course of HCV-related arthritis does not justify the therapeutic use of anti-TNF." (PMID 22312391, 2010). "However, there is no clear scenario of balance between IL-6 and TNFα in arthritis." (PMID 19660107, 2009). "In the inflammatory context, where TNF-α and IFN-γ are prominent, induction of proinflammatory cytokines may reverse the cytokine balance, leading to a reversion of the immunosuppressive capacity of MSC as we previously showed in the collagen-induced arthritis model of arthritis." (PMID 16277684, 2005). "Thus, JNK1 activation does not seem to be essential for TNF-mediated arthritis." (PMID 15642137, 2005). "Thus, overexpression of TNF-α induces clinical signs of arthritis also in the absence of JNK1." (PMID 15642137, 2005). "This research described the antioxidant (SOD3, CAT, GPX, ATOX1 and COX18) and immunological (IL-1α, IL-1β, IL-6, IL-10, TNFα, NCF4, NFKB, TMED, FCAMR and iNOS) genes in rams that had arthritis and those that did not." (PMID 40005882, 2025). "For instance, the administration of TNF-α inhibitors during the preclinical stage does not suppress disease development, likely because TNF-α plays a more prominent role during the arthritis (clinical) phase, as discussed later." (PMID 41010616, 2025). "Changes occurring following castration that were independent of testosterone included BALF levels of TNF-α and CXCL2, lung levels of MMP-8, TIMP-1, and C5a, and lung autoantigen expression as well as lung cellular infiltrates and arthritis severity." (PMID 38086040, 2024). "This interpretation is supported by the findings that the deletion of the TNF-α gene does not confer complete protection from the occurrence of arthritis in CIA and that TNF-α and IL-17 act independently of each other under arthritic condition." (PMID 38650931, 2024). "In addition, the adjuvant–induced arthritis (AIA) rat model was employed, and the results exhibited that pristimerin could effectively relieve arthritis symptoms and histopathological damage as well as reduce serum levels of TNF-α, NO and synovial expressions of p-Akt and p-Erk in AIA rats." (PMID 36144243, 2022).
Arthritis (continued). "Their arthritis is chronic, and unlike arthritis in non-WTC-exposed sarcoid patients, inadequately responsive to conventional oral DMARDs, often requiring TNF inhibitors." (PMID 35943526, 2022). "Treating the 5-mo-old DNase II−/−STINGS365A/S365A mice with anti–IL-6R reduced the arthritis score and the expression of IL-6 and MMP-3 but did not reduce the expression of TNF-α, CXCL1, and CXCL2." (PMID 34901991, 2022). "A murine model of chronic arthritis, in which mice lacking VDR were interbred with human tumor necrosis factor (TNF) transgenic mice, showed that the absence of VDR exacerbated inflammation and the severity of arthritis." (PMID 35276806, 2022). "VP treatment decreased gut TNF expression with no change for IL6, thus reflecting the immunomodulatory effect of VP described in arthritis." (PMID 34956224, 2021). "Mediators for inflammation, except TNFα and IL-1, were increased in synovial washouts during SCW arthritis, but none of the inflammatory mediators (KC, MCP-1, IL-6) were significantly different between WT and S100a9−/−." (PMID 32854769, 2020). "Our data suggest that in particular females under anti-TNF treatment and patients suffering from non-joint and/or IBD-related surgery should be close and carefully monitored for presence of arthritis or sacroiliitis/ankylosing spondylitis." (PMID 31039159, 2019). "Although not statistically significant, the concentrations of TNF-α, IL-1β, and MDA tended to be lower in A77 1726-treated arthritis mice than in vehicle (DMSO)-treated animals." (PMID 28193225, 2017). "The citrullinating enzyme peptidylarginine deiminase 4 (PAD4) exacerbates TNF-α-induced arthritis, but a role for PAD4 in lung citrullination and TNF-α-induced lung inflammation has not been explored." (PMID 27450561, 2016). "Despite our observation that TNF-α induces lung citrullination, we found that TNF-α-driven lung inflammation is not sufficient to induce arthritis." (PMID 27450561, 2016). "In the murine glucose-6-phosphate isomerase-induced arthritis model, for example, treatment with MTX does not result in decreases in either IL-6 or TNF alpha." (PMID 24444433, 2014). "Three patients were on DMARDs (1 MTX, 2 SSZ), two in combination with an NSAID, one was on the anti-TNF agent etanercept, five were on an NSAID only, and three required no medication for their arthritis." (PMID 23844402, 2013). "None of the indicated parameters including TNFα, PGE2 and arthritis scoring was changed in control AIA rats receiving DMSO (data not shown) or control animals receiving ramipril alone." (PMID 23079082, 2012). "However, because TNF is not the main actor in STA, there were no consequences of anti-LTα3 treatment, as anti-LTα3 alone did not inhibit arthritis in +/+ mice." (PMID 40650132, 2025). "As might be expected, key pro-inflammatory cytokine USRs such as TNF, IFNG, IL6, and IL1B that were upregulated during CHIKV arthritis were downregulated (negative z-scores) in the ameliorated foot swelling seen in Gzma-/- mice." (PMID 35119362, 2022). "Zymosan caused systemic inflammation with a marked elevation in multiple pro- and anti-inflammatory cytokines TNF-α, IFN-γ, IL-13, G-CSF, M-CSF, IL-6, IL-18, IL-1α and IL-4 in arthritic rats (all arthritis groups pooled) versus the non-arthritic controls (0.001<p<0.05)." (PMID 33878143, 2021). "Because TNF is one of the key main mediators of inflammation, it is no surprise that alterations of its physiologic antagonist PGRN have a direct impact on the initiation and progression of arthritis." (PMID 27428882, 2016). "In addition, we designed the study to be able to introduce a TNF-inhibitor early in the disease course if DAS-remission was not achieved, also for patients with arthritis who were suspected to have early RA, who did not fulfil the classification criteria." (PMID 26794605, 2016).